SNORD115-26 (small nucleolar RNA, C/D box 115-26)
Synonyms: HBII-52-26
Gene: Small nucleolar RNA gene on chromosome 15 (25,218,617 to 25,218,698, forward strand). Ensembl gene ENSG00000275524.
Gene Ontology:
Biological process: RNA processing
Cellular component: nucleolus
Homologues: Orthologues: chimpanzee SNORD115 (100% identical). Paralogues in human: SNORD115-11 (99% identical), SNORD115-29 (99% identical), SNORD115-36 (99% identical), SNORD115-41 (99% identical), SNORD115-43 (99% identical), SNORD115-12 (98% identical), SNORD115-16 (98% identical), SNORD115-22 (98% identical), SNORD115-31 (98% identical), SNORD115-39 (98% identical), SNORD115-44 (98% identical), SNORD115-6 (98% identical), and 37 more.